AKR1B1 (aldo-keto reductase family 1 member B)
Diseases named in the same sentence as AKR1B1 in open-access papers (continued):
Sharing a sentence is not in itself a finding about the gene and the disease.
cancer (continued). "AKR1B1 was widely expressed in multiple kinds of cancers, suggesting that the polyol pathway is an active and essential feature of cancer metabolism." (PMID 39406918, 2024). "Overexpression of EBF1 inhibited cancer cell proliferation, but overexpression of AKR1B1 reversed the inhibitory effect of EBF1 on cell growth." (PMID 36397644, 2023). "Overexpression of Akr1b1 has been observed in multiple cancer types and is thought to increase Warburg effects by triggering the AKT/mTOR signaling pathway." (PMID 36681715, 2023). "To gain mechanistic insights into the AKR1B1 effects on GC cell migration and proliferation and the prospective regulatory mechanism of the AKT-mTOR pathway, we firstly retrieved AKR1B1 expression in GC clones through the Cancer Cell Line Encyclopedia (CCLE)." (PMID 37751590, 2023). "Our current study identified the ZNF521/EBF1/AKR1B1 axis, which is hyperactivated in GC and plays important role in promoting cancer cell growth, migration, and invasion." (PMID 36397644, 2023). "Researchers observed that AKR1B1 expression was aberrantly increased in malignant tumors, and its expression level affected the survival prognosis of patients." (PMID 37751590, 2023). "According to the cell viability analysis, AKR1B1 knockdown exacerbated cancer cell growth time-dependently." (PMID 37185746, 2023). "The aberrant AKR1B1 protein expression in human tissues has been related to the initiation and progression of various chronic diseases and cancers." (PMID 37751590, 2023). "AKR1B1 and AKR1B10 have been associated with different cancers; however, their roles differ among cancer types." (PMID 35159076, 2022). "Aberrant expression of AKR1B1 resulted in the activation of various signaling pathways such as NFκB, an ubiquitous transcription factor found in various cancer." (PMID 36301939, 2022). "We finally observed a significant positive correlation between AKR1B1 expression and immune infiltration in two cancer species: STES (N = 569, R = 0.24, p = 5.5 × 109), STAD (N = 388, R = 0.45, p = 1.2 × 1020)." (PMID 36140749, 2022). "AKR1B1 overexpression has been shown to strongly correlate with the molecular profile of mesenchymal-like cells in various cancer models." (PMID 36463238, 2022). "On the basis of these facts, it can be observed that both AKR1B10 and AKR1B1 are aberrantly expressed in different cancer so there is a need to explore potential inhibitors of both targets." (PMID 36301939, 2022). "Then, by in-depth analyzing the characteristics of mixed-lineage cancer cells, we identified gene signatures specific to mixed-lineage cancer cells, including AKR1B1." (PMID 35962452, 2022). "The median and mean percentages of AKR1B1-positive cancer cells were 85.0% and 69.4%, respectively (IQR = 60.0, SD = 34.0)." (PMID 35159076, 2022). "The median and mean percentages of AKR1B1-positive cancer cells were 50.0% and 51.6% for endometrioid EC and 50.0% and 58.8% for serous EC." (PMID 34298614, 2021). "Several studies have been conducted on measuring AKR1B1 expression to find out more about its role in cancer." (PMID 32633024, 2020). "In in vitro experiments, they detected increased AKR1B1 levels in mesenchymal-like cancer cells, while AKR1B1 knockdown was sufficient to revert EMT." (PMID 33302403, 2020). "Here, increased SORD activity in adenomas and cancer cell lines lead to changes in expression of AKR1B1 and KHK." (PMID 33302403, 2020).
cancer (continued). "The other cancer-associated markers APC and AKR1B1 showed relatively high methylation levels in epithelial cell lines, whilst no methylation was observed in mesenchymal cell lines." (PMID 30154364, 2018). "Four enzymes (TPI1, AKR1B10, ALDOA, and AKR1B1) out of 34 enzymes in this pathway are overexpressed in cancer." (PMID 25243088, 2014). "In the current study, we aimed to understand whether AKR1B1 is expressed solely by cancer cells or also by other cell types in the TME, and whether its expression from the TME contributes to the prediction of prognosis." (PMID 40396420, 2025). "In the KEGG enrichment score, a total of seven signaling pathways, including cell adhesion molecules cams, chemokine-signaling pathway, and other related pathways in cancer, are active in the high AKR1B1 expression group, while olfactory transduction is active in the low AKR1B1 expression group." (PMID 40978044, 2025). "Furthermore, AKR1C2, AKR1C3, and AKR1B1 knockdown attenuated the proliferation and invasive ability of cancer cells." (PMID 40361399, 2025). "Emerging evidence also suggests a role for AKR1B1 in cancer biology, where it may influence pathways regulating inflammation, apoptosis, chemoresistance, and cell cycle progression." (PMID 41154825, 2025). "Differential expression of AKR1B1 was seen in benign and malignant tumors of the adrenal cortex." (PMID 39055885, 2024). "We found that all cancer and control cell lines expressed varying levels of AKR1B1." (PMID 39406918, 2024). "However, the exact mechanisms by which AKR1B1-mediated endogenous fructose metabolism governs cell cycle progression and cancer cell migration require further investigation." (PMID 39406918, 2024). "While AKR1B1 has been documented in other types of cancer, its impact on BLCA remains unreported." (PMID 39749345, 2024). "According to our results, AKR1B1 inhibitors could be potential drugs for preventing cancer metastasis in diabetic patients." (PMID 38200154, 2024). "The polyol pathway is not crucial for energy metabolism in normal cells and inhibiting AKR1B1 activity could be a viable and safe cancer treatment approach." (PMID 39406918, 2024). "To determine whether the glucose level affects the activation of the polyol pathway, we compared the expression of AKR1B1 in cancer cells of A549 and U87 cultured under different glucose levels." (PMID 39406918, 2024). "Clinical trials are testing AKR1B1 inhibitors for diabetic complications and these compounds may have potential as direct cancer treatments and preventive treatments for diabetic patients." (PMID 39406918, 2024). "In some cases, AKR1B1 inhibitors could be used for dual purposes to inhibit diabetic complications or cancer exacerbation." (PMID 38200154, 2024). "AKR1B1 and ITGAV have been associated with drug resistance associated EMT in cancer." (PMID 37174052, 2023). "Moreover, ZNF521 knockdown‐mediated elevation of EBF1 expression resulted in downregulation of AKR1B1 and subsequent inhibition of cancer cell proliferation, migration, and invasion." (PMID 36397644, 2023). "In cancer studies, AKR1B1 strongly correlates with aggressive and invasive cancer." (PMID 36552555, 2022). "Therefore, in order to reduce the aggressiveness of cancer, AKR1B1 is an important target for drug development." (PMID 36552555, 2022). "Notably, AKR1B1 strongly correlates with epithelial-to-mesenchymal transition (EMT) and is linked to glucose metabolism, cancer differentiation, and aggressiveness." (PMID 36195845, 2022).
cancer (continued). "Moreover, AKR1B1 regulates cancer migration and invasion through the conversion of prostaglandin H2 (PGH2) to prostaglandin F2α (PGF2α) and the activation of the epithelial–mesenchymal transition (EMT) process." (PMID 36552555, 2022). "It was suggested that AKR1B1 overexpression may render cancer cells resistant to anticancer drugs and that AKR1B1 inhibitors could reverse this resistance." (PMID 35159076, 2022). "In addition, the expression of MMP2 in AKR1B1 knockdown cancer cells also decreased significantly compared with the control group." (PMID 34646828, 2021). "Thus, there is an urge to conduct more clinical studies on the application of AKR1B1 inhibitors as adjuvant therapy on different cancers." (PMID 32633024, 2020). "This may prove a point that AKR1B1 could have a role in cancer promotion through NFκB activation, which has the ability to promote tumorigenicity in several cancers." (PMID 32633024, 2020). "Several studies have also suggested that AKR1B1 inhibition as an adjuvant therapy could render tumour cells more sensitive to anti‐cancer therapy or alleviate the adverse effects of therapy." (PMID 32633024, 2020). "Thus, there is a need to conduct more clinical studies on the application of AKR1B1 inhibitors as adjuvant therapy on different cancers." (PMID 32633024, 2020). "Several lines of information indicated that both up and down‐regulation of AKR1B1 could take part in drug resistance in cancer." (PMID 32633024, 2020). "Their findings point to the great potential of AKR1B1 inhibition as novel cancer therapeutics." (PMID 23734127, 2013). "Therefore, it has been hypothesized that the role of AKR1B1 in maintaining an aggressive phenotype in cancer cells may be mediated by catalytic-independent mechanisms." (PMID 40309007, 2025). "However, the role of AKR1B1 in brain cancer remains unclear, but growing evidence suggests that it has a large impact on cancer therapy." (PMID 37185746, 2023). "In addition, inhibition of AKR1B1 has been shown to mostly have anti‐cancer effects." (PMID 32633024, 2020). "Furthermore, inhibition of AKR1B1 could render cancer cells more sensitive to anti‐cancer therapy or alleviate the adverse effects of therapy." (PMID 33292266, 2020). "In another study including 39 cell lines and 64 anti‐cancer drugs, AKR1B1 expression alteration induced the tumour cells to become more sensitive to 23 out of 64 drugs, suggesting that AKR1B1 expression could be a putative marker for chemosensitivity prediction." (PMID 32633024, 2020). "Although the various roles of AKR1B1 have been identified in different metabolic and physiological processes, such as glucose metabolism, inflammation and prostaglandin synthesis, its true function in cancer still remains unknown." (PMID 32633024, 2020). "Because conceptus and cancer cells possess various characteristics in common such as EMT and angiogenesis, it is considered that CAPG and AKR1B1 included in conceptus-derived exosomes could be involved in the conceptus attachment similar to those demonstrated in cancer adhesion and/or invasion." (PMID 27351483, 2016). "Specifically, increases in methylated AKR1B1, HIST1H3C and TM6SF1 during treatment were found to be correlated with a higher Residual Cancer Burden (RCB)." (PMID 38245552, 2024). "Immunohistochemical staining showed that the expression of STC1, AKR1B1, and CD47 was increased along cancer invasion." (PMID 36816947, 2023). "The TCGA data bank was analysed by the GEPIA platform based on the numerous analogous influences of AKR1B1 and AKT-mTOR on cancer cells." (PMID 37751590, 2023). "In this study, we have selected and comprehensively evaluated the expression of four commonly known EMT markers (E-cad, N-cad, VIM, TGFβ1), and four unconventional EMT markers (α-SMA, AKR1B1, ITAV, G6PD), less studied in cancer in relation to the EMT process." (PMID 37174052, 2023).
cancer (continued). "Compared to TN and MPR patients, we observed that enzymes in the Aldo-Keto Reductase family (AKR1B1/10 and AKR1C1-3) were highly expressed in cancer cells from NMPR patients." (PMID 36869384, 2023). "AKR1A1, AKR1B1, and 13 other genes in STAD (TCGA, PanCancer Atlas) were analyzed using cBioPortal for Cancer Genomics." (PMID 36827074, 2023). "Meanwhile, EDNRA, PRRX1, EMP1, AKR1B1, and SULF2 exerted an important role in cancer progression in other tumor types." (PMID 36816947, 2023). "The expression of STC1, AKR1B1, RPL5, and CD47 was increased, while HLA-A was downregulated along cancer invasion by immunohistochemical staining in clinical samples." (PMID 36816947, 2023). "Levels of AKR1B1 in non‐cancerous gastric epithelial cells (GES‐1) and GC cells (AGS and NCI‐N87) were determined and were revealed to be significantly higher in cancer cells than in normal cells." (PMID 36397644, 2023). "Immunohistochemic3al staining showed the expression of STC1, AKR1B1, and CD47 was increased along cancer invasion in CRC samples." (PMID 36816947, 2023). "Recently, (−)KU was predicted as an inhibitor of AKR1B1, the new target that plays an important role in cellular oxidative stress and the EMT process on cancer cells." (PMID 36552555, 2022). "In resistant cancer cells, elevated expression of G6PD, AKR1B1 and GFPT2 counteracts the effects of ROS production as a prerequisite for cell survival and therapy resistance." (PMID 36463238, 2022). "Our data suggest that AKR1B1 is involved in the pathogenesis of HGSC and is a potential prognostic biomarker for this cancer." (PMID 35159076, 2022). "Hence, inhibition of AKR1B1 could assist to treat cancer by reducing tumour growth." (PMID 32633024, 2020). "Hence, AKR1B1 inhibition might be useful in the treatment of cancer." (PMID 32633024, 2020). "In the same study, the reduction of AKR1B1 led to a decrease in AKT/mTOR signalling and cancer development in mice." (PMID 32633024, 2020). "Among other genes that were clustered with STS were several genes with ubiquitous expression in the normal tissues and documented overexpression in cancers: SLC26A6, TOMM40L, AKR1B1, NDRG2 and DGAT1 (based on TCGA data)." (PMID 29088719, 2017). "This revealed up to 12 genes that are suppressed in CRC, including genes that had been previously found misregulated in cancer, such as HPGD, PTGIS, PTGER3, and AKR1B1." (PMID 26207152, 2015). "Five enzymes (LDHB, MDH2, PKM2, AKR1B1, and AKR1B10) out of 40 enzymes in pyruvate metabolism pathway are overexpressed in cancer." (PMID 25243088, 2014). "The article by Laffin and Petrash (2012) examines the expression of AKR1B1 and AKR1B10 across all major human cancer types." (PMID 23734127, 2013). "Within cyclic imides group of inhibitors, the most utilized ARIs are Fidarestat and Sorbinil, both have been shown to suppress AKR1B1-driven EMT processes in both cancer and non-tumor contexts." (PMID 41154825, 2025). "Clinical research has largely focused on AKR1B1 and AKR1B10 with very little emphasis on other members that could shed light on specific pathways and cellular processes that are specific to cancer type and tissue of origin." (PMID 39055885, 2024). "Finally, we found that the expression of STC1, AKR1B1, and CD47 was increased along cancer invasion in clinical CRC samples using immunohistochemical staining." (PMID 36816947, 2023). "Many studies demonstrated that AKR1B1 and AKR1B10 are involved in different cancers." (PMID 34298614, 2021). "Since aldose reductase (AKR1B1) has a similar structure to AKR1B10 and is involved in glucose and prostaglandin metabolism, developing inhibitors as anti-cancer drugs or adjuvant therapies for chemotherapeutic drug resistance must ensure selective inhibition of AKR1B10." (PMID 34063865, 2021).
cancer (continued). "Although pre‐clinical investigations on the role of AKR1B1 in cancer and the application of its inhibitors have shown promising results, the lack of clinical studies on AKR1B1 inhibitors has hampered the use of these drugs to treat cancer." (PMID 32633024, 2020). "The role of aldo‐keto reductase family 1 member B1 (AKR1B1) in cancer is not totally clear but growing evidence is suggesting to have a great impact on cancer progression." (PMID 32633024, 2020). "Since AKR1B1 could increase tumorigenesis by inducing cell cycle progression in CRC, its inhibition could be used as a therapeutic approach in the treatment of cancer." (PMID 32633024, 2020). "Although pre‐clinical investigations on the role of AKR1B1 in cancer and the application of its inhibitors have shown promising results, the lack of clinical studies on AKR1B1 inhibitors on cancer has hindered the use of these drugs." (PMID 32633024, 2020). "The role of AKR1B1 in BC not clear but growing studies are suggesting to AKR1B1 have an important impact on cancer progression." (PMID 33292266, 2020). "AKR1B1’s homologue AKR1B10 is overexpressed in multiple cancer types, including malignancies of breast, prostate and lungs, and is deemed suitable as a target in cancer treatment." (PMID 29532688, 2018). "Also aldo-keto reductases AKR1B1 and AKR1B10 enriched in cancer ESTs catalyze reduction of D-glyceraldehyde to glycerol and 2-hydroxypropanal to propane-1,2-diol in glycerolipid metabolism." (PMID 25243088, 2014). "(±)-KU has an anti-cancer effect and could bind with CSF1R and AKR1B1." (PMID 37959760, 2023). "On the other hand, AKR1B1 (SMD = 0.3; 95% CI 0.01; 0.60; P < 0.01), CTSK (SMD = 1.52; 95% CI 0.98; 2.06; P < 0.01), MMP2 (SMD = 1.02; 95% CI 0.51; 1.53; P < 0.01), TLR4 (SMD = 0.85; 95% CI 0.34; 1.37; P < 0.01) were up-regulate in cancer groups, which might be the tumor proto-oncogene." (PMID 34646828, 2021).